SOX4 (SRY-box transcription factor 4)
Diseases named in the same sentence as SOX4 in open-access papers (continued):
Sharing a sentence is not in itself a finding about the gene and the disease.
prostate carcinoma (continued). "The results showed that mRNA and protein levels of SOX4 in prostate cancer tissues were significantly higher than those in normal tissues, indicating that SOX4 was highly expressed in prostate cancer tissues." (PMID 34863188, 2021). "Correlation between expression of β-catenin and SOX4 and clinicopathological features of prostate cancer." (PMID 34157052, 2021). "In fact, SOX4 inhibition reduces AKT and β-catenin pathways activation and decreases prostate cancer invasiveness through positive feedback loop between SOX4 and PI3K-AKT-mTOR." (PMID 29888169, 2018). "We have shown that deletion of SOX4 in vivo can inhibit prostate cancer progression and that the knockdown of SOX4 can induce apoptosis in prostate cancer cells." (PMID 30314329, 2018). "Several of the identified targets genes are known mediators of prostate cancer cell “stemness” and self-renewal, such as NKx3.1, BMI-1, and SOX-4; some are also embryonic stem cell (ESC) regulators, such as KLF4 and SOX2." (PMID 26046794, 2015). "Our results concord with reports in which SOX4-KO in adenoid cystic carcinoma and prostate cancer cells induced apoptosis." (PMID 26555193, 2015). "Knock down of SOX4 induced apoptosis in prostate cancer cells and adenoid cystic carcinoma ACC3 cells." (PMID 25366337, 2014). "Our model identified several transcription factors associated with prostate cancer metastasis, such as ETS2, HOXC4, STAT3, STAT5B, SOX4 and ZEB2." (PMID 23782521, 2013). "Our results were consistent with those in bladder and prostate cancers, and showed that nuclear SOX4 expression was elevated in colon tumor tissues relative to non-tumor colon tissues." (PMID 23826209, 2013). "SOX4 is also upregulated at the mRNA and protein level in prostate cancer and this upregulation is correlated with higher Gleason score or tumor grade." (PMID 22098624, 2011). "To investigate the cellular functions of SOX4, we have developed a one-step affinity purification method that enables rapid purification of SOX4 complexes in LNCaP cells, a prostate cancer cell line." (PMID 22098624, 2011). "It has been reported that SOX4 is frequently amplified and overexpressed in various malignancies, strongly supporting the notion that SOX4 is an oncogene, including in breast, bladder, and prostate cancers." (PMID 40595502, 2025). "SOX4 has been shown to be upregulated in various cancers, including colorectal, breast, and prostate cancer, where it promotes tumorigenesis and progression by activating critical signaling pathways such as transforming growth factor-beta (TGF-β) and Wnt/β-catenin." (PMID 40595502, 2025). "Also of interest were several genes associated with prostate cancer metastases including FOXA1, EZH2, SCHLAP1, CDH1, SOX4, SOX9, HOXB13, and TGFBR3." (PMID 38067373, 2023). "SOX4 facilitates the growth and impedes the apoptosis in prostate cancer cells." (PMID 35112991, 2022). "miRNA-214-5p inhibits the proliferation of prostate cancer cells in vitro by targeting SOX4." (PMID 34863188, 2021). "Besides, SOX4 transcriptionally activates the expression of miR‐17‐92 cluster in prostate cancer progression." (PMID 34427967, 2021). "However, the specific knockdown of SOX4 through SOX4 shRNA significantly reduced the proliferation of prostate cancer cell lines." (PMID 34863188, 2021). "Data suggest a transcriptional regulatory effect of SOX4 on genes of multiple pathways that may play roles in prostate cancer progression." (PMID 34316327, 2021). "In view of the role of SOX4 in prostate cancer, if we try to inhibit the expression of SOX4 in vivo, it may also alleviate the development of prostate cancer." (PMID 34863188, 2021). "Also of note, the developmental transcription factor SOX4, upregulated in DU145, has been shown to possess oncogenic activity in prostate cancer, wheres Nestin has been associated with the drug resistant prostate stem population." (PMID 28038472, 2017).
prostate carcinoma (continued). "While SOX4 expression is elevated in many malignancies and is tightly correlated with prostate cancer tumor grade, little is known of the mechanism by which SOX4 affects the progression of prostate cancer." (PMID 22098624, 2011). "Therefore, in the next study, we need to investigate whether SOX4 expression changes in the mouse model can inhibit the growth of prostate cancer tissue in vivo." (PMID 34863188, 2021). "The results showed that transfection of miRNA-214-5p mimics in prostate cancer cell lines DU-145 and PC-3 could significantly reduce the expression of SOX4 mRNA and protein, indicating that miRNA-214-5p may directly affect SOX4 gene." (PMID 34863188, 2021). "Therefore, SOX4 may become the next potential clinical drug target for prostate cancer." (PMID 34863188, 2021). "Among these hsa-miR-204-5p target genes, SIRT1, SOX4, and RUNX2 exhibited a tumor-suppressive/oncogenic role in previous prostate cancer studies." (PMID 34512726, 2021). "In particular, SOX4 regulates EZH2 expression and chromating remodeling, and is a key component of the PI3K/AKT pathway in prostate cancer." (PMID 29888169, 2018). "Data suggest that ERG regulates the transcription of the transcription factor SOX4 and together they cooperate in TGF-β1-induced EMT of prostate cancer cells." (PMID 29888169, 2018). "Our study showed that knocked-down SOX4 suppressed tumor cell invasion and migration in HNSCC cells; earlier studies showed it to significantly inhibit invasiveness and migration in prostate cancer cells." (PMID 26555193, 2015). "Additional studies will be required to elucidate the detailed mechanisms by which SOX4-plakoglobin interactions may affect Wnt signaling, but the role of the SOX4-plakoglobin complex provides novel insights into the role of SOX4 in Wnt signaling and prostate cancer progression." (PMID 22098624, 2011). "The results of this study also showed that the expression of SOX4 in prostate cancer tissues was significantly higher than that in non-cancer tissues." (PMID 34863188, 2021). "Immunohistochemistry studies of 85 prostate cancer cases revealed also complete absence of SOX-4 nuclear expression in 19 (22.4%) of specimens, weak SOX-4 nuclear expression in 61 (71.7%) and high nuclear expression of SOX-4 in 5 patients (5.9%)." (PMID 34157052, 2021). "Moreover, SOX4 was shown to interact with ERG itself and promote EMT in prostate cancer cells." (PMID 34708244, 2022). "Since the target of miRNA may not be unique, in addition to the host factor SOX4, miRNA-214-5p may have other target genes, and the combination of these genes is the key to the development of prostate cancer." (PMID 34863188, 2021). "Indeed, by knocking down PHF19L, we observed significant induction of multiple genes known to promote changes in cytoskeleton and adhesion, extracellular matrix remodeling, invasion, and metastasis in prostate cancer (including SOX9, SOX4, MMP1, PLAU, EPCAM, CXCR4, LOX, and MET)." (PMID 32155117, 2020).
colorectal cancer (37 papers, 2009 to 2026). A primary or metastatic malignant neoplasm that affects the colon or rectum. "METTL14 reportedly curbs the metastasis of colorectal cancer cells by inhibiting the m6A modification of SRY-box transcription factor 4 (SOX4) mRNA, a mechanism reliant on the YTHDF2-mediated mRNA degradation pathway." (PMID 40746896, 2025). "For example, METTL14-mediated m6A on the SOX4 transcript in colorectal cancer inhibits SOX4 expression and metastasis; low METTL14 permits SOX4 protein upregulation and is associated with metastatic relapse." (PMID 41301491, 2025). "Further studies would clarify the effects of the increased expression of SOX4 with tumorigenesis and progression in colorectal cancer." (PMID 38528462, 2024). "This study finds that lncRNA PCGEM1 and SOX4 are overexpressed in colorectal cancer, while miR-129-5p is underexpressed." (PMID 36193492, 2022). "For instance, SOX4 is validated to accelerate the growth, migration and invasion of colorectal cancer cells." (PMID 35112991, 2022). "PCGEM1 mediates the proliferation, invasion, and migration of colorectal cancer cells by targeting miR-129-5p and regulates the expression of SOX4." (PMID 36193492, 2022). "In conclusion, PCGEM1 mediates the proliferation, invasion, and migration of colorectal cancer cells by targeting miR-129-5p/SOX4 axis." (PMID 36193492, 2022). "In colorectal cancer, SOX4 has been reported as a target gene of some miRNAs, including miRNA-212, miRNA-130a, miRNA-133a, and miRNA-539." (PMID 36193492, 2022). "The results of rescue experiments confirmed that SOX4 served as the functional protein of PCGEM1/miR-129-5p in colorectal cancer." (PMID 36193492, 2022). "Upregulated expression of SOX4 in colorectal cancer was identified in our study, which was consistent with previous researches." (PMID 36193492, 2022). "But for colorectal cancer, what is the potential target gene for miR-129-5p, bioinformatics analysis was used again in our study, and SOX4 was found." (PMID 36193492, 2022). "In our study, cell functional studies and dual luciferase activity assay confirmed the existence of miR-129-5p/SOX4 axis in colorectal cancer." (PMID 36193492, 2022). "Meanwhile, it has been reported that lncRNA ZFAS1 contributes to the metastasis of colorectal cancer by regulating miR-34b/SOX4 axis." (PMID 34496348, 2021). "miR-363-3p suppresses metastasis and inhibits the epithelial-to-mesenchymal transition (EMT) in colorectal cancer by targeting Sox4." (PMID 33744854, 2021). "SOX4 can promote the invasion and migration of colorectal cancer cells through the epithelial-mesenchymal transition (EMT) process and PI3K/AKT signaling pathway." (PMID 33926508, 2021). "Overexpression of SOX4 promotes sphere formation and self-renewal of colorectal cancer cells in vitro and in vivo and elevates the expression levels of CSCs markers." (PMID 33482915, 2021). "In malignant melanoma and colorectal carcinoma, miR-140-5p was confirmed to be suppressed cell proliferation and invasion by inhibiting SOX4 expression." (PMID 32127028, 2020). "We also found that SOX4 was a downstream target of miR-133a and ABHD11-AS1 subsequently exerted its biological effects via modulating the expression of SOX4 in colorectal cancer cells." (PMID 30429229, 2018). "In addition, METTL14 is significantly downregulated in colorectal cancer and inhibits the malignant process of colorectal cancer through the SOX4-mediated EMT process and PI3K/Akt signaling." (PMID 38725005, 2024). "SOX4 overexpression promotes sphere formation and the self-renewal of colorectal cancer cells, which directly bind to the HDAC1 promoter, encouraging HDAC1 transcription and thereby stem cell maintenance, Wnt, Notch, the cell cycle, and transcriptional misregulation pathways in cancer." (PMID 39228892, 2024). "Furthermore, rescue experiments indicated that lncRNA PCGEM1 can regulate colorectal cancer proliferation, invasion, and migration through targeting miR-129-5p/SOX4." (PMID 36193492, 2022).
colorectal cancer (continued). "In addition, overexpressing SOX4 can increase the invasion and migration ability of colorectal cancer cell, which means that SOX4 can act as a cancer-promoting gene for colorectal cancer." (PMID 36193492, 2022). "At first, the sample size of clinical patients is not large enough, and more follow-up data need to be collected to further evaluate the relationship between the expression levels of lncRNA PCGEM1, miR-129-5p, and SOX4 in colorectal cancer tissues and patient prognosis." (PMID 36193492, 2022). "In addition, this study only conducted in vitro cell experiments and clinical tissue detection; in vivo experiments in animal models are needed to further clarify the role of lncRNA PCGEM1/miR-129-5p/SOX4 regulatory axis in colorectal cancer." (PMID 36193492, 2022). "SOX4 is overexpressed in colorectal cancer cells and tissues." (PMID 36193492, 2022). "In colorectal cancer, SOX4 serves as the target of METL14-mediated m6A modification." (PMID 33926508, 2021). "Nevertheless, some of these circRNAs have established biological roles in other tumor cells, e.g., circCDYL facilitates the progression of cervical cancer by targeting the miR-211-5p/SOX4 axis and inhibits colorectal cancer cell proliferation and migration via the miR-382-5p/PTEN axis." (PMID 34680287, 2021). "To validate the effects of JIB-04 on the mRNA expression of β-catenin target genes, we measured the mRNA levels of CSC-associated genes (CD44, LGR5, DKK1, ALDH1A3, ALDH1B1, CD24, and SOX4) by qRT-PCR in three different colorectal cancer cell lines after treament with JIB-04." (PMID 29700375, 2018). "Collectively, these findings manifested that the ABHD11-AS1/miR-133a/SOX4 axis may be a cogitable and promising therapeutic target for colorectal cancer." (PMID 30429229, 2018). "As an oncogene, SOX4 overexpression predicts poor outcome of colorectal cancer." (PMID 25366337, 2014). "Furthermore, miRNA-130a may increase the radiosensitivity of rectal cancer cells by directly targeting SOX4; since T2DM has been associated with a 1.3-fold increased risk of colorectal cancer, further research in this field is warranted too." (PMID 33008044, 2020). "Mechanically, PCGEM1 acted as a sponge for miR-129-5p and absorbed its expression, and miR-129-5p was found to target SOX4, constructing the axis of PCGEM1/miR-129-5p/SOX4 in colorectal cancer." (PMID 36193492, 2022). "HDAC1 hallmarks colorectal cancer stem cells and depletion of HDAC1 abolished the stimulatory effect of SOX4." (PMID 33482915, 2021). "The mechanistic study showed that SOX4 directly binds to the promoter of HDAC1, promotes HDAC1 transcription, thereby supporting the stemness of colorectal cancer cells." (PMID 33482915, 2021). "SOX4 was previously shown to enhance beta-catenin/TCF activity and the proliferation of colorectal cancer cells." (PMID 25366337, 2014). "A previous study revealed that miR-363-3p is involved in the metastasis of colorectal cancer by functioning as a tumor suppressor through the negative regulation of its target Sox4 gene." (PMID 33744854, 2021). "In this study, by identification of SOX4-induced proteome changes in colorectal cancer stem cells (CRC-SCs), we investigated the potential molecular effects of SOX4 in CRC-SCs and found that SOX4 transcriptionally regulates HDAC1 to support the stemness of CSCs." (PMID 33482915, 2021). "Earlier studies showed that KCNQ1OT1 promoted NSCLC progression by modulating miRNA-27b-3p/HSP90AA1 axis, and stimulated cholangiocarcinoma development via miR-140-5p/SOX4 axis, and facilitated the migration and EMT of colorectal cancer by forming a feedback loop with miR-217 and ZEB1." (PMID 32821247, 2020).
colorectal cancer (continued). "The direct targets of miR-187 include the homeobox transcription factor, Sox4, which also contributes to EMT, and so, the effects of miR-187 against TGFβ signaling and Sox4 may explain why miR-187 is downregulated in colorectal cancer cells." (PMID 27367735, 2016). "Furthermore, SOX4 promotes tumor invasion and metastasis by upregulating LEM domain containing 1, which activates the PI3K/Akt signaling pathway in colorectal cancer, implying that SOX4 may facilitate NSCLC progression through a similar mechanism." (PMID 41268614, 2026). "Interestingly, interrogation of the expression levels of this gene panel (SOX4, FOXM1, and FOXQ1) in The Cancer Genome Atlas (TCGA) colorectal cancer data set (319 patients) revealed significantly poor disease-free survival in patients with elevated expression of this gene panel (P-Value: 0.0058)." (PMID 27119506, 2016). "Interestingly, interrogation of the expression of this identified gene panel (SOX4, FOXM1, and FOXQ1) in The Cancer Genome Atlas (TCGA) Colorectal cancer data set revealed significantly shorter disease-free survival in patients with elevated expression of these genes (Logrank Test P-Value: 0.00581)." (PMID 27119506, 2016). "However, the axis of miR-129-5p/SOX4 in colorectal cancer has not been reported yet." (PMID 36193492, 2022). "As AMBRA1 affected CTNNB1 transcription via ALDH1B1, which is a crucial CSC marker of colorectal cancer, we next investigated whether AMBRA1 expression affects the mRNA levels of several CSC-related β-catenin target genes, including LGR5, HIF1a, ALDH1A3, CD24, and SOX4." (PMID 34769507, 2021).